CHEK2 (checkpoint kinase 2)
Diseases named in the same sentence as CHEK2 in open-access papers (continued):
Sharing a sentence is not in itself a finding about the gene and the disease.
breast cancer (continued). "Several large-scale studies have characterized known variants of the CHEK2 gene, conclusively proving that CHEK2 is a breast cancer susceptibility gene." (PMID 18706089, 2008). "Checkpoint Kinase 2 (CHEK2) is an important signal transducer of cellular responses to DNA damage, whose defects have been associated with an increase in breast cancer risk." (PMID 18706089, 2008). "In the current study, we examined a panel of 25 BRCA1/2 negative, affected French Canadian women alongside 25 healthy controls, to investigate the impact of CHEK2 variants on breast cancer susceptibility in the French Canadian population." (PMID 18706089, 2008). "A recent example of such an approach has been seen with the identification of the CHEK2 S428F mutation in the Ashkenazi Jewish population, which has been associated with a relative breast cancer risk of 2.0 amongst Ashkenazi Jewish women." (PMID 18706089, 2008). "We have evaluated the prevalence of the CHEK2 1100delC variant in two cohorts of breast cancer patients from the Stockholm region, one familial and one population-based, both with a well-defined family history and in controls." (PMID 17705858, 2007). "A rare truncating variant in CHEK2 (1100delC), a G2 checkpoint-kinase, that is involved in cell cycle control and DNA-repair, was identified as a risk factor for breast cancer in two independent studies using this approach." (PMID 17705858, 2007). "A fifth gene, CHEK2, in the same pathway, has a deletion (1100delC) that reaches polymorphic frequencies (>0.01) in some European countries and doubles the risk of breast cancer in female carriers." (PMID 17428325, 2007). "One particular sequence variant in CHEK2 (CHEK2*1100delC) has been implicated in a twofold increased risk of breast cancer, functioning as a low-penetrance breast cancer susceptibility allele." (PMID 17428320, 2007). "In a recent study, based on a consecutive series of breast cancer patients under 50 years of age, unselected for family history, we showed that CHEK2*1100delC carriers have a twofold increased risk of second breast cancer." (PMID 17428320, 2007). "A truncating variant, 1100delC, in check point-kinase CHEK2, has been identified as a risk factor for familial and sporadic breast cancer." (PMID 17705858, 2007). "We genotyped the CHEK2 1100delC gene mutation in our study population and have previously reported its effect on the overall risk of breast cancer." (PMID 17132159, 2006). "Among the two women with the CHEK2 1100delC allele in our study, one presented with two separate, synchronous, breast cancers." (PMID 16539695, 2006). "An approximately 2-fold increased risk of breast cancer has been associated with the CHEK2 1100delC mutation." (PMID 16539695, 2006). "At least 1/10 of breast cancers and colorectal cancers occur because of heredity and recently the cell cycle kinase 2, CHEK2 1100delC allele has been identified at a particularly high frequency in families with hereditary breast and colorectal cancer." (PMID 16539695, 2006). "A protein-truncating variant of CHEK2, 1100delC, is associated with a moderate increase in breast cancer risk." (PMID 15700044, 2005). "Here, we have assessed the frequency of CHEK2 1100delC variant among familial breast cancer cases from Australia and have analysed the expression, phosphorylation and activity of CHK2 in LCLs from heterozygous individuals." (PMID 15700044, 2005). "This study design can not exclude the involvement of a rare allele in predisposition to breast or ovarian cancer; for example, CHEK2*1100delC, has a frequency of around 1% and was recently shown to confer a two-fold increased risk of breast cancer." (PMID 16029503, 2005). "From recent publications, it appeared that the germline CHEK2*1100delC mutation in fact confers low-penetrance susceptibility to breast cancer." (PMID 14970869, 2004).
breast cancer (continued). "The association between the CHEK2 1100delC variant and risk for breast cancer was initially reported by the CHEK2 Breast Cancer Consortium." (PMID 15535844, 2004). "In the case of CHEK2, the truncating variant 1100delC confers a relative risk of breast cancer approximately two-fold; this relative risk appears to be independent of FH, and this gene fits well as a component of a multiplicative polygenic model." (PMID 15381934, 2004). "We report here on the frequency of three CHEK2 variants that alter protein function – 1100delC, R145W, and I175T – in 506 cases and 459 controls from a population based, case–control study of breast cancer conducted in young women from western Washington." (PMID 15535844, 2004). "The truncating germline mutation CHEK2*1100delC abrogates kinase activity and confers low-penetrance susceptibility to breast cancer." (PMID 14970869, 2004). "Several previously published studies reported an elevated frequency of the CHEK2 1100delC variant in specific stratifications of breast cancer patients." (PMID 15535844, 2004). "In sporadic (osteo)sarcomas, lung cancers, breast cancers, ovarian cancers, colon cancers and haematopoietic neoplasms, CHEK2 was found to be rarely mutated." (PMID 14970869, 2004). "This variant conferred no increased cancer risk among BRCA1/2 carriers or sporadic cases (The CHEK2-Breast Cancer Consortium., 2002)." (PMID 15138485, 2004). "We analyzed three CHEK2 variants that are known to disrupt protein function (1100delC, R145W, and I175T) in a population based, case–control study of breast cancer among young North American women." (PMID 15535844, 2004). "Originally, germline mutations in CHEK2 gene were reported in Li–Fraumeni syndrome and breast cancer." (PMID 14612911, 2003). "We have recently shown that the CHEK2*1100delC mutation acts as a low penetrance breast cancer susceptibility allele." (PMID 12454775, 2002). "We have recently found evidence for this model with the observation that the 1100delC variant in CHEK2 which is carried by ∼1% of the population confers a 1.7-fold increased risk of breast cancer." (PMID 12454775, 2002). "The way in which mutations in CHEK2 cause breast cancer is likely to be through mechanisms other than the loss of heterozygosity that is observed with other classical tumour suppresser genes." (PMID 12454775, 2002). "To investigate if other CHEK2 variants confer an increased risk of breast cancer, we have screened an affected individual with breast cancer from 68 breast cancer families." (PMID 12454775, 2002). "Odds ratios were calculated by comparing cancer incidence (any cancer, multiple primary cancer, breast cancer, and bilateral breast cancer) among participants with a monoallelic PV in CHEK2 and those with PV and LR variant, and the differences were not statistically significant." (PMID 39745704, 2025). "Case 4 with breast cancer at the age of 48 years had CHEK2 c.1100delC and MCPH1 c.909_921del alleles, and her father, diagnosed with prostate cancer (age unknown) and lung cancer (84 years), was also identified as a double carrier." (PMID 40009290, 2025). "CHEK2 germline PVs/LPVs are considered as moderate-risk factors for breast cancer." (PMID 40429818, 2025). "However, when meta-analyzing our results with previous studies, CHEK2 c.1100delC was still associated with a worse breast cancer-specific survival." (PMID 41314031, 2025). "Comparisons of individuals with biallelic variants in CHEK2 were made with WT (n = 33 034), as well as LR variant heterozygotes (n = 1566) or PV heterozygotes (n = 2167) for any cancer, multiple primary cancers, breast cancer, and bilateral breast cancer." (PMID 39745704, 2025). "However, after those 6 years, CHEK2 c.1100delC was associated with a worse distant disease-free survival (HR = 2.7; 95 %CI = 1.8–3.9) and breast cancer-specific survival (HR = 2.1; 95 %CI = 1.4–3.0)." (PMID 41314031, 2025).
breast cancer (continued). "Moreover, in an exploratory analysis of grouping genes that were previously reported to predispose toward ER-positive disease, use of E + P MHT was modestly associated with high breast cancer risk in women with ATM or CHEK2 PVs." (PMID 40298171, 2025). "This approach is particularly valuable when counseling individuals with variants in moderate-penetrance breast cancer genes like CHEK2, ATM, RAD51C, RAD51D, and BARD1, since the relative effect of risk factors is expected to be higher than in individuals with high-penetrance PVs." (PMID 40805171, 2025). "Furthermore, a recently published study on breast cancer patients with any CHEK2 pathogenic variant showed a similar breast cancer-specific survival compared to the average genetically tested patients, which supports our current findings." (PMID 41314031, 2025). "In addition to breast cancer, CHEK2 mutations are linked to an increased risk of other malignancies, including colorectal, prostate and thyroid cancers." (PMID 41049353, 2025). "CHEK2 variants are also known to increase the risk of breast cancer, leukemia, and other cancers." (PMID 40283643, 2025). "Given the small number of PVs, we jointly analyzed two moderate penetrance genes, ATM and CHEK2, due to their shared association with ER-positive breast cancer in prior studies; the result of this exploratory analysis was an increase in breast cancer risk (OR = 7.3) associated with E + P MHT." (PMID 40298171, 2025). "CHEK2 c.1100delC is associated with an increased breast cancer risk in women." (PMID 39384226, 2024). "On the basis of mutated genes in cBioPortal database, which was targeted sequencing of 2509 primary breast tumors with 548 matched normal tissues, a total of 30 genes including BBC driver mutations BRCA1, BRCA2, CHEK2 and other high frequency mutations in breast cancer were represented." (PMID 38800414, 2024). "Both the ATM, PALB2 and CHEK2 genes are breast cancer susceptibility genes of moderate penetrance." (PMID 38504328, 2024). "The CHEK2 mutations have previously been reported in breast cancer." (PMID 38784039, 2024). "Protein-truncating or rare missense variants in coding regions of CHEK2, especially 1100delC (rs555607708), have been previously reported to have moderate penetrance for overall breast cancer risk and ER + breast cancer in familial studies and population based studies." (PMID 38515142, 2024). "Thus, CHEK2, as well as other genes included in the human Fanconi anemia/breast cancer-associated (FANC/BRCA) pathway, which is involved in DNA damage-repair responses, shows an apparent concentration of positive selection." (PMID 38338903, 2024). "Further evidence suggests a potential genetic link between thyroid cancer and breast cancer, with studies in Poland showing a four-fold increase in thyroid cancer risk following a breast cancer diagnosis, rising to a nine-fold increase in women carrying a CHEK2 mutation." (PMID 39001408, 2024). "BRCA1 and BRCA2’s PVs were associated with breast cancer, ovarian/fallopian cancer, pancreas cancer, prostate cancer, and melanoma, while breast, prostate, thyroid, kidney, colon and stomach cancers were related to PVs in CHEK2." (PMID 38929805, 2024). "This mutation has been described in less heterogeneous populations, as in studies conducted in the Netherlands that described the increased risk of breast cancer observed in patients with CHEK2 1100delC and another study that reported 4% of their tested patients carrying this pathogenic variant." (PMID 38504328, 2024). "The CHEK2 breast cancer risk was variable for different PVs." (PMID 38929805, 2024). "The strongest association signal exclusively associated with early-onset infertility was a frameshift mutation (rs555607708, c.1100delC [GenBank: NM_007194.4] [p.Thr367MetfsTer15]) in CHEK2, which previously has been shown to confer increased risk for breast cancer." (PMID 39566493, 2024).
breast cancer (continued). "•Carriers developed early-onset ER + breast cancer, a signature of CHEK2 mutations." (PMID 38554551, 2024). "On the other hand, we showed that coupling the identification of a variant in ATM or CHEK2 with the calculation of a PRS might effectively identify women most at risk of breast cancer." (PMID 39669587, 2024). "Individuals with high-risk CHEK2 variants and a strong family history of breast cancer may benefit from a pre-emptive or contralateral risk-reducing mastectomy." (PMID 39642869, 2024). "Pathogenic variants in the CHEK2 gene increase the risk of breast cancer." (PMID 39126233, 2024). "Germline mutation of CHEK2 has been associated with both breast cancer and CRC." (PMID 39202750, 2024). "Furthermore, we were only able to investigate the molecular profile for CHEK2-deficient cancers of 4 origins beyond breast cancer." (PMID 38848470, 2024). "The CHEK2 gene has a moderate penetrance, representing a 20–40% lifetime risk for breast cancer." (PMID 39684258, 2024). "Additionally, breast cancer patients carrying the CHEK2 p.H371Y mutation are more likely to respond to neoadjuvant chemotherapy compared to non-carriers [PMID: 25884806]." (PMID 39411129, 2024). "Germline pathogenic/likely pathogenic variants (GPVs) in CHEK2 are typically associated with a moderately increased risk of breast cancer in females, generally in the range of 20–30% lifetime risk of breast cancer and a relative risk (RR) of >2." (PMID 39062660, 2024). "For instance, one of the common CHEK2 mutations associated with breast cancer is c.1100delC." (PMID 38242891, 2024). "Germline CHEK2 pathogenic variants confer an increased risk of female breast cancer (FBC)." (PMID 38554551, 2024). "Canonical breast-cancer-associated genes with pathogenic germline mutations were CHEK2 and ATM." (PMID 37239898, 2023). "We then collected 12 case–control datasets from the ENIGMA consortium members, including 161,706 patients with breast cancer and population-matched controls from 10 countries, and examined the breast cancer risk for carriers of functionally stratified CHEK2 missense variants." (PMID 37449874, 2023). "The case–control analysis revealed that the breast cancer risk of functionally impaired germline variants is comparable with that of truncating CHEK2 P/LP variants and suggested that the clinical management of (breast) cancer prevention in both groups of carriers should be similar." (PMID 37449874, 2023). "CHEK2 is a well-established breast cancer susceptibility gene." (PMID 36653541, 2023). "The authors concluded that 6.8% of the (European) breast cancer patients and 2.0% of the controls had protein truncating variants in the genes associated with breast cancer risk and 2.2% of the patients and 1.4% of the controls had missense variants in CHEK2." (PMID 36882784, 2023). "This is in line with findings in moderate breast cancer risk genes such as CHEK2, PALB2 and ATM and suggests that PRS inclusion in risk stratification may in particular be relevant to prevent excess of surveillance measures in PV carriers of those genes." (PMID 36872334, 2023). "Breast cancer patients with CHEK2 mutations have 2-3-fold increased risk of thyroid cancer." (PMID 37434214, 2023). "The prevalence of germline CHEK2 variants differs among patients with breast cancer worldwide." (PMID 37449874, 2023). "In addition, we find that breast cancer patients with either somatic or germline mutations in CHEK2 are more likely to be diagnosed with metastatic than primary ER+/HER2− breast cancer." (PMID 37390209, 2023). "Thus, we demonstrate that the breast cancer risk associated with functionally impaired CHEK2 missense variants is comparable with the risk associated with P/LP truncating variants." (PMID 37449874, 2023). "However, a recent large case–control study of the Breast Cancer Consortium has established the evidence of an increased risk of BC in rare missense variants in CHEK2." (PMID 38476463, 2023).
breast cancer (continued). "Consequently, similar carrier frequencies in the studied cases and the general population argue against association of CHEK2 p.(Asp438Tyr) with increased breast cancer risk." (PMID 36653541, 2023). "In second place were variants of CHEK2 (14, 9.8%), which associated with breast cancer (7.7%)." (PMID 38201513, 2023). "GPVs in ATM and CHEK2 confer a moderate risk of breast cancer." (PMID 37258796, 2023). "CHEK2 c.1100delC was the first moderate-risk breast cancer (BC) susceptibility allele discovered." (PMID 37161532, 2023). "Approximately 19% of thyroid cancers after breast cancer are attributable to CHEK2 mutations." (PMID 35205705, 2022). "Approximately 6% of breast cancer patients in Poland carry a CHEK2 mutation." (PMID 35205705, 2022). "Lastly, the CHEK2 gene variant (E239K, rs121908702) was initially identified in men with prostate cancer but has also had conflicting association with cases and controls in two separate breast cancer cohorts." (PMID 36315513, 2022). "A multicentre association study involving more than 113 000 women associated truncating variants in CHEK2 with an increase in breast cancer risk [odds ratio of 2.13 (1.60–2.84)] furthermore influenced by the ER status of the tumor [ER+ tumors 2.67 (95% CI, 2.3–3.11)]." (PMID 36568162, 2022). "However, other contributing factors for this association need to be investigated such as defects in homologous recombination (e.g., BRCA1, BRCA2, PALB2, ATM, CHEK2) known to increase risk of breast cancer." (PMID 36421330, 2022). "In addition, more frequent, but less penetrant germline mutations have been identified in families with breast cancer in genes such as CHEK2, ATM, PALB2, and BRIP1." (PMID 35333900, 2022). "CHEK2 has been recognized as a breast cancer risk gene with moderate effect." (PMID 33468213, 2021). "Given truncating CHEK2 PGVs have been associated with a relative risk of breast cancer of 2.2,9 a high risk of contralateral disease, and are enriched in this cohort and others, this would substantiate inclusion of testing for CHEK2 PGVs in clinical diagnostic breast cancer genetic testing panels." (PMID 34113003, 2021). "Specifically, germline pathogenic CHEK2 variants, excluding the low-risk variants, p.(Ile157Thr) and p.(Ser428Phe), known to be associated with much lower risk, confer an approximate lifetime risk for breast cancer diagnosis of about 25–30% in females." (PMID 33925588, 2021). "The risk of breast cancer associated with CHEK2:c.1100delC is 2–threefold but higher in carriers with a family history of breast cancer than without, suggesting that other genetic loci in combination with CHEK2:c.1100delC confer an increased risk in a polygenic model." (PMID 34285278, 2021). "While the majority of pathogenic germline variants in CHEK2 are associated with a moderately increased risk of breast cancer, certain variants may confer a higher risk of disease, and others with a more modest risk." (PMID 34771713, 2021). "A risk prediction model, the Breast and Ovarian Analysis of Disease Incidence and Carrier Estimation Algorithm (BOADICEA) has been developed to calculate the lifetime risk of breast cancer, including carriers of a moderate-penetrance allele such as CHEK2:c.1100delC." (PMID 34285278, 2021). "By conducting a population-based case-control-family study of pathogenic CHEK2 variants we aimed to provide this information and estimated the penetrance (age-specific cumulative risk) of breast cancer to be 18% (95% CI 11–30%) to age 60 years and 33% (95% CI 21–48%) to age 80 years." (PMID 33803639, 2021). "Homozygosity for the CHEK2 PV is rare, but seems to be associated with a higher breast cancer risk." (PMID 33468213, 2021).